IMPDH1 (inosine monophosphate dehydrogenase 1)
Diseases named in the same sentence as IMPDH1 in open-access papers (continued):
Sharing a sentence is not in itself a finding about the gene and the disease.
tumor (continued). "We next explored the lung tissue expression of IMPDH1 and IMPDH2 among normal (n = 391), tumor (n = 1,865), and metastatic (n = 8) tissue samples from data available within TNMplot." (PMID 39366383, 2024). "IMPDH1 and ISG20 were mainly expressed in tumor cells, while the remaining genes were less specific to tumor cell origin." (PMID 36816023, 2023). "In particular, we observed that the fold change in IMPDH1 expression in tumours compared to normal tissues was significantly higher than the fold change in IMPDH2 expression in CRC, implying a pivotal role for IMPDH1 in tumourigenesis." (PMID 36629054, 2023). "Nude mice were injected subcutaneously with 5637 cells knocked down IMPDH1 and IMPDH2 to construct the subcutaneous tumor model." (PMID 37215997, 2023). "It was shown that IMPDH1 was one of the isoforms of inosine-5′-monophosphate dehydrogenase (IMPDH) which contributed to the formation of cytoophidia and tumor progression." (PMID 36816023, 2023). "Exogenous supplementation with mycophenolic acid (MPA), a drug that inhibits IMPDH1, suppresses the malignant phenotype of ICC, inhibits the secretion of inflammatory factors, and ultimately alleviates tumor growth in ICC." (PMID 36711025, 2023). "Lastly, the wet-lab qRT-PCR experiments compared the mRNA expressions of PPAT, ATIC, IMPDH1, DCK, and RRM2 in between 10 pairs of human primary HCC tissues and neighboring non-tumor liver tissues." (PMID 33520699, 2020). "In addition, protein levels of IMPDH1 and IMPDH2 in mouse tumor tissues were markedly down-regulated by MMF (p < 0.001), but were only fine-tuned by GDNT." (PMID 38419324, 2024). "In addition, we found that with the evolution of tumor cell status, the expression levels of FLT3LG, GALNT10, IL1B, and IMPDH1 remained stable while ISG20 gradually increased." (PMID 36816023, 2023). "Furthermore, depletion of IMPDH1 in HCC cells inhibited the capability to formulate single-cell colonies in vitro and reduced tumor initiation and growth efficiency in immunodeficient mice." (PMID 35992798, 2022). "In addition, We also performed multivariate cox analysis of IMPDH1, age, gender, TNM stage and tumor grade in HCC patients." (PMID 36618420, 2022). "Interestingly, IMPDH1 has been shown to be ubiquitously expressed in many different tissues, while IMPDH2 is upregulated in proliferating tissues, which could include DMG tumor tissue." (PMID 38594734, 2024). "Finally, we found that IMPDH1 may be a key gene in tumorigenesis, whose expression may help shape the TME and promote tumor progression." (PMID 36816023, 2023). "We unexpectedly found that when IMPDH1/2 was knocked down at the animal level, the expression of IMP, GMP, and GTP was abnormally high, which may be related to the reduced consumption of IMP, GMP, and GTP in the tumor." (PMID 37215997, 2023). "However, there is still a lack of study on IMPDH1 evaluating its role in the tumor immune microenvironment, the potential mechanisms, and its potential as a promising tumor therapeutic target." (PMID 36618420, 2022). "We observed that the expression of IMPDH1 and IMPDH2 did not correlate within patient samples and between tumor site." (PMID 39366383, 2024). "Consistently, in tumor cells used in our study, IMPDH2 mRNA levels were significantly higher than IMPDH1 mRNA levels although in non-transformed counterparts of these cells the IMPDH2/IMPDH1 level ratio was not as high." (PMID 34667203, 2021). "Note that in the absence of tumor formation at day 3, the expression of PPAT, IMPDH1, IMPDH2, DHODH but not PAICS are all statistically significantly elevated with MYC induction." (PMID 18628958, 2008). "One recent study observed a large increase in IMPDH2 but not IMPDH1 in GBM compared to control brains and proposed IMPDH2 as the molecular link between GTP biosynthesis, the increased anabolic process of rRNA and tRNA, and tumor malignancy in GBM." (PMID 38892179, 2024).
tumor (continued). "The results showed that the expression levels of FLT3LG, GALNT10, IL1B, IMPDH1 and ISG20 were higher in tumor cells than in normal cells, while the remaining genes could not be identified because of the low expression levels in tumor cells." (PMID 36816023, 2023).
cancer (20 papers, 2019 to 2025). A tumor composed of atypical neoplastic, often pleomorphic cells that invade other tissues. "Our comprehensive Pan‐cancer study revealed that these enzymes are dysregulated in various cancers and are associated with Myc/Myc signatures, particularly IMPDH1." (PMID 36629054, 2023). "However, a thorough investigation is necessary to elucidate the specific roles and underlying mechanisms of IMPDH1 in the context of cancer." (PMID 38702629, 2024). "In order to explore whether the expression level of IMPDH1 correlated with patient survival, we assessed overall survival of cancer patients associated with IMPDH1 expression level in pan-cancer by using TCGA datasets." (PMID 36618420, 2022). "Overall, IMPDH1 as an independent risk prognostic factor, could be used to predict a variety of cancer patients survival prognosis, such as HCC." (PMID 36618420, 2022). "We evaluated m-6-A modified protein, which showed IMPDH1 was closely related to m-6-A related regulatory proteins in pan-cancer, and we focused on evaluating the association of IMPDH1 with the top four proteins: YTHDF1, ALKBH5, YTHDF2, METTL3 in HCC, indicating a strong relationship." (PMID 36618420, 2022). "RNA-seq data from the Human Protein Atlas reveal widespread IMPDH2 overexpression compared to IMPDH1 across many cancer cell lines." (PMID 41154443, 2025). "Employing various online tools, including TIMER2.0, UALCAN, and GEPIA, an extensive analysis of IMPDH1 gene mRNA expression across various cancer types was performed." (PMID 38702629, 2024). "The findings revealed elevated IMPDH1 expression in over two-thirds of pan-cancer cases compared to adjacent normal tissues." (PMID 38702629, 2024). "Taken together, these data support the idea that the Myc–IMPDH1/2 axis plays a crucial role in tumourigenesis and suggests IMPDH1/2 as viable targets for cancer treatment." (PMID 36629054, 2023). "As a proof‐of‐concept exemplification, we demonstrated that IMPDH1 is significantly overexpressed in cancer through Pan‐cancer analyses and cellular/molecular experiments." (PMID 36629054, 2023). "Impressively, TK1, RRM2 and IMPDH1 were positively correlated with Myc/Myc signatures in multiple cancer types, whereas HSD17B6, PYGM and ACACB were negatively correlated with Myc/Myc signatures." (PMID 36629054, 2023). "In this study, we established a link between the 168 metabolic rate‐limiting enzymes and Myc and identified the dysregulation of the Myc–IMPDH1/2 axis in human cancers." (PMID 36629054, 2023). "Particularly, we analyzed the correlation between IMPDH1 expression and treatment responsiveness, prognosis of cancer patients receiving immunotherapy." (PMID 36618420, 2022). "In the ImmuCellAI database, monocytes were confirmed to be the most common immune cells positively correlated with IMPDH1 in pan-cancer, while the most common negatively correlated cells were CD8+T and gamma delta T cells." (PMID 36618420, 2022). "More importantly, the expression level of IMPDH1 makes a considerable contribution to the treatment response and prognosis of cancer patients receiving immunotherapy." (PMID 36618420, 2022). "The findings also showed that the mRNA expression levels of TM4SF1, FASN, and IMPDH1 were higher in cancer tissues, whereas the mRNA expression of KCNJ15 was higher in normal tissues." (PMID 35480865, 2022). "Protein‐protein interaction analysis further revealed that IMPDH1 was involved in many cancer‐related pathways." (PMID 35403278, 2022). "Through bioinformatics analysis, we found that IMPDH1 was in a state of high expression in many tumors, and the cancer tissues were mostly higher than the paired adjacent tissues." (PMID 36618420, 2022). "Compared with para-carcinoma tissues, IMPDH1 had a higher expression in HCC tissues, reflected by qRT-PCR result of 11 primary HCC patients." (PMID 36618420, 2022). "Our results propose the inhibition of IMPDH1 as a viable option for cancer treatment." (PMID 36629054, 2023).
cancer (continued). "We observed the dysregulation of the Myc–IMPDH1/2 axis in eight cancers, including CRC." (PMID 36629054, 2023). "Our findings proposed that the inhibition of the Myc–IMPDH1/2 axis or IMPDH1 may be a viable option for cancer treatment, especially CRC." (PMID 36629054, 2023). "To confirm whether the Myc–IMPDH1/2 axis is dysregulated in cancers, we performed a single‐sample gene set enrichment analysis in human cancers." (PMID 36629054, 2023). "However, the role of IMPDH1 in cancer, especially in CRC, has been largely ignored because IMPDH1 is less expressed than IMPDH2 in most tissues." (PMID 36629054, 2023). "Here, we propose the inhibition of IMPDH1 as a viable option for cancer treatment." (PMID 36629054, 2023). "IMPDH1 is highly expressed in a variety of cancers and usually predicts a poor prognosis." (PMID 36618420, 2022). "In pan-cancer research, there was a strong correlation between IMPDH1 and m-6-A modified protein." (PMID 36618420, 2022). "In summary, significant correlation between monocytes, macrophages, CD8+T cell, gamma delta T cell and IMPDH1 in pan-cancer could be found in these databases." (PMID 36618420, 2022). "Finally, we utilized a flow chart to show the research route of IMPDH1 in pan-cancer more intuitively." (PMID 36618420, 2022). "More importantly, these genes particularly IMPDH1 are targetable in cancer treatment." (PMID 33520699, 2020). "Moreover, we confirmed that the Myc–IMPDH1/2 axis is dysregulated in human cancers." (PMID 36629054, 2023). "Finally, we confirmed that the Myc–IMPDH1/2 axis is dysregulated across human cancers." (PMID 36629054, 2023). "Since the significant results of HCC in the pan-cancer study of IMPDH1, and HCC is the fourth leading cause of cancer-related mortality in China, with large patient population, which suggest HCC might be the most representative cancer in pan-cancer for IMPDH1 study." (PMID 36618420, 2022). "The enzymes involved in purine metabolism are overexpressed in various cancer, such as adenosine deaminase (ADA), cytoplasmic-5’-nucleotidase-II (CN-II) and inosine monophosphate dehydrogenase (IMPDH1)." (PMID 39343971, 2024). "RALGPS1, NUDT9, NUDT2, and PDE4A were less expressed in cancer cell lines; JUP, ADA, HPRT1, and IMPDH1 were highly expressed in cancer cell lines in CCLE." (PMID 34745385, 2021). "Among them, four genes (PPAT, ATIC, IMPDH1, and RRM2) belong to the purine de novo biosynthesis pathway which is indispensable for cancer cell proliferation." (PMID 33520699, 2020). "There are two isotypes of IMPDH in humans, IMPDH isotype 1 (IMPDH1) and IMPDH isotype 2 (IMPDH2), of which IMPDH2 has been reported to be more highly upregulated in cancers." (PMID 33224873, 2020). "IMPDH1 is constantly expressed, while IMPDH2 is inducible and frequently overexpressed in cancer." (PMID 41154443, 2025). "It was found that one of the isoforms of IMPDH, IMPDH1, may be expressed in both normal and cancer cells, but IMPDH2 is expressed preferably in cancer-transformed cells." (PMID 37175852, 2023). "We also verified the protein expression and subcellular localization of IMPDH1 in HCC patients cancer and paired non-cancer tissues by Immunohistochemistry (IHC), and supported by IHC results from “The Human Protein Atlas”, which were consistent with the results of bio-informatics analysis." (PMID 36618420, 2022). "Therefore, we analyzed the correlation of methylation level with IMPDH1 expression in pan-cancer, showing negative correlation in 28 kinds of tumors." (PMID 36618420, 2022). "Given that all 16 enzymes analyzed localized to the leading edge and colocalized with IMPDH1 and/or IMPDH2, our data suggests the formation of a GTP- and possibly also an ATP-specific metabolic compartment—GTP and ATP metabolons, respectively—at the leading edge of the motile cancer cells." (PMID 33224873, 2020). "However, the role of IMPDH1 in cancer has not been well studied." (PMID 35403278, 2022).
cancer (continued). "We observed that IMPDH1, but not the related gene IMPDH2, was significantly overexpressed in all 15 cancers, implying the key role of IMPDH1 in tumourigenesis." (PMID 36629054, 2023). "Here, we found that IMPDH1, but not the related gene IMPDH2, was significantly overexpressed in 15 cancer types." (PMID 36629054, 2023). "Unlike IMPDH1, IMPDH2 expression is increased in neoplastic cells, and modulation of IMPDH2 levels alters intracellular GTP pools and affects cancer cell proliferation and/or invasion." (PMID 34667203, 2021).
retinopathy (3 papers, 2018 to 2024). "Multiple point mutations on human IMPDH1 have been identified associated with the retinopathy adRP10." (PMID 29946345, 2018). "Interestingly, RP10 mutations have been suggested to be gain-of-function mutations, as Impdh1-knockout mice present mild retinopathy." (PMID 38227383, 2024). "Several IMPDH1 mutations in CBS domains are known to be related to retinopathy adRP10." (PMID 29946345, 2018). "RP10 mutations are allegedly ‘gain-of-function’ mutations, given that IMPDH1 knock-out mice present only a mild retinopathy." (PMID 32254022, 2020).
cardiovascular disease (1 paper, 2022). "As reported, IMPDH1 function as the catalyzes in the development of multiple organs and progression of cardiovascular disease." (PMID 36401332, 2022).
infection (1 paper, 2025). The state of being infected such as from the introduction of a foreign agent such as serum, vaccine, antigenic substance or organism. "The variant of IMPDH1 -106C>A (rs2278294) and c.1575G>A (rs2228075) were strongly associated with infection susceptibility and GI intolerance, such as nausea, vomiting, and diarrhea." (PMID 40630120, 2025). "This reduction in IMPDH1 activity may enhance the pharmacodynamic effects of MPA, thereby intensifying immunosuppression and predisposing patients to infection." (PMID 40630120, 2025).
IMPDH1 also shares sentences with these, for which no sentence is quoted: Leber congenital amaurosis 11 (4 papers); liver cancer (2); acute lymphoblastic leukaemia (1); adenocarcinoma (1); anaplastic large cell lymphoma (1); anemia (1); brain cancer (1); Breast Invasive Carcinoma (1); ciliopathies (1); Coffin-Siris syndrome (1); colon cancer (1); cystoid macular edema (1); diffuse large B-cell lymphoma (1); esophageal squamous cell carcinoma (1); gastric cancer (1); head and neck cancer (1); heart failure (1); hematological cancers (1); intrahepatic cholangiocarcinoma (1); lung adenocarcinoma (1); lung fibrosis (1); mantle cell lymphoma (1); melanoma (1); metastatic tumors (1); microcephalic osteodysplastic primordial dwarfism type II (1); microphthalmia (1); multiple myeloma (1); multiple sclerosis (1); non-small cell lung carcinoma (1); pancreatic cancer (1).
A further 7 diseases each share a sentence with IMPDH1 in 1 paper.